NOTCH1 (notch receptor 1)
Diseases named in the same sentence as NOTCH1 in open-access papers (continued):
Sharing a sentence is not in itself a finding about the gene and the disease.
adenoma (21 papers, 2005 to 2025). A neoplasm arising from the epithelium. "VN-/- mice, which lack Notch-1 specifically in the intestinal epithelium, developed spontaneous mucinous colorectal tumors associated with adenoma/low-grade dysplasia, high-grade dysplasia, goblet cell hyperplasia and serrated changes." (PMID 30323897, 2018). "In addition, activation of Notch-1 signaling in APCMin mice converted high-grade adenomas into low-grade adenomas along with suppression of about 40% of tumor-associated genes, particularly genes involved in Wnt signaling." (PMID 30323897, 2018). "Furthermore, Notch1 itself was downregulated in Ap4-deficient adenomas." (PMID 30177706, 2018). "This promotes the development of cancer through the adenoma–carcinoma sequence or through the overexpression of NOTCH1 in cases of papillary renal carcinoma type 2." (PMID 39064555, 2024). "This function predicts that Notch1+ lineages will persist in adenomas and continue to slowly expand even after 90 days, indicating self-renewal capacity." (PMID 30696875, 2019). "Activation of NOTCH1 converted high-grade adenoma into low-grade adenoma in an APCmin mouse colon cancer model." (PMID 27938406, 2016). "These hyperplastic regions progressed to adenomas with papillary histology in doxycycline-fed Notch1 mice." (PMID 25004243, 2014). "There were significantly more cases (110 and 135) with low expression of Notch1 in ulcerative colitis and adenoma tissue." (PMID 24312514, 2013). "Expression of Notch1 was examined in the cytoplasm of benign tissues (normal adjacent, ulcerative colitis, adenoma tissue) and cancer tissues." (PMID 24312514, 2013). "Quantitative PCR revealed decreased Notch 1 mRNA in ovarian adenocarcinomas compared with adenomas." (PMID 16136053, 2005). "The observation that adenoma initiation in the ApcMin/+ intestines required Jag1-induced Notch signaling suggested that either Jag1 was the only Notch ligand expressed in the adenomas, or adenoma-specific Notch1 was refractory to the induction by other ligands such as Dll4." (PMID 30065304, 2018). "The only existing studies in the ApcMin/+ adenomas indicated that the expression of Notch receptors and ligands was similar to that observed in the crypts, Hes1 was detected uniformly and Jagged1 was overexpressed in the tumor tissue with concomitant Notch1 and 2 activation." (PMID 28086833, 2017). "Remarkably, positive correlations between the expression of NOTCH1-2,4 and the HES1 target gene, and between NOTCH3 with the ligand JAGGED1 were found in the cohort of samples used when all adenomas were considered, independently of tumor histotype." (PMID 28915655, 2017). "Levels continued to increase over time through to adenoma formation, and also in the ADC samples from the Notch1-Myc mice." (PMID 25004243, 2014). "IHC analysis of samples using the ICN1 antibody demonstrated higher Notch1 activity in adenoma and carcinoma samples compared with normal adjacent mucosa of the same patients." (PMID 34831152, 2021). "The observation of a consistent expression of Notch 1 protein in ovarian adenocarcinomas and adenomas does not prove that Notch 1 signalling is actually active." (PMID 16136053, 2005). "Comparatively, in adenomas, ≥2-fold Notch3 expression was detected in 56% followed by Notch1 (44%), Notch4 (33%), and Notch2 (11%), while for ligand Jag1, mRNA was overexpressed in 33%, Jag2, Dll1, and Dll3 in 11%, whereas Dll4 was not expressed in adenomas." (PMID 32211044, 2020). "This analogous effect of NOTCH1 and -2 has also been found in tumors from Familial Adenomatous Polyposis (FAP) patients and might be representative of the behavior of these receptors in the conventional adenoma-carcinoma pathway according to several in vitro studies." (PMID 37860822, 2023).
lymph node metastasis (21 papers, 2011 to 2025). "In CRC, elevated Notch1 expression is associated with lymph node metastasis, while reduced Notch2 expression predicts poor prognosis." (PMID 40438109, 2025). "Increased NOTCH1 is associated with tumor differentiation, depth of tumor invasion, lymph node metastasis, and Lauren classification." (PMID 33452458, 2021). "The association of NOTCH1 mutations with tumor stage and lymph node metastasis also held true in this cohort (P < 0.0001)." (PMID 26528858, 2016). "NOTCH1 expression was associated with an increased risk of lymph node metastasis and a worse overall survival." (PMID 26394830, 2015). "Increased NOTCH1 expression was associated with lymph node metastasis, which is in line with previously reported data." (PMID 26394830, 2015). "The meta-analysis indicated that higher expression of Notch1 was associated with greater possibility of lymph node metastasis and higher TNM stages." (PMID 25996086, 2015). "NOTCH1 mutated were related lymph node metastasis (p = 0.005) and related to age (p = 0.002)." (PMID 35127817, 2021). "Furthermore, the relevance of NOTCH1 mutations to lymph node metastasis was confirmed in our previously published cohort #3 (P = 0.011)." (PMID 26528858, 2016). "NOTCH1 expression was associated with lymph node metastasis." (PMID 26394830, 2015). "For Notch1, statistically significant associations were observed between its strong immunohistochemical expression in neoplastic cells and perineural infiltration (p = 0.011) and with lymph node metastasis (p = 0.034) of patients with poorly differentiated OSCCs." (PMID 33854547, 2021). "The expression of Notch-1 and Numb was correlated with the lymph node metastasis, TNM stage, and degree of differentiation (p<0.05)." (PMID 39691600, 2024). "In summary, strong immunoexpression of Notch1 can contribute to the identification of patients with poorly differentiated OSCCs who have perineural infiltration and lymph node metastasis." (PMID 33854547, 2021). "The results revealed that the upregulation of Notch1 signaling was positively correlated with lymph node metastasis in patients with PTC (OR = 3.25, 95% CI 1.14–9.23, P = 0.03)." (PMID 30622441, 2019). "A meta-analysis showed that Notch1 was correlated with lymph node metastasis, TNM stages and significantly poor OS in NSCLC patients." (PMID 28061457, 2017). "The expression level of NOTCH1 negatively correlated with lymph node metastasis and predicted longer patient survival (n = 101)." (PMID 26491213, 2015). "In the subgroup of patients with early tumor stages (n = 64), NOTCH1 expression was the second most important factor (HR: 0.82, 95% CI: 0.67–0.99, p = 0.038) after lymph node metastasis (HR: 3.35, 95% CI 1.30–8.68, p = 0.013)." (PMID 25954607, 2015). "The status of Notch-1 expression, along with histological phenotype, lymph node metastasis and tumor differentiation, were found to be significantly associated with survival of LAD patients (P = 0.033, 0.002, 0.021 and 0.016, respectively)." (PMID 24423157, 2013). "We found that NOTCH1 mutations were only associated with lymph node metastasis in young ESCC patients, which may be used for the diagnosis of early lymph node metastasis in ESCC." (PMID 35127817, 2021). "Another report claimed that highly expressed DLX6-AS1 was associated with lymph node metastasis and poor prognosis of OC patients, and downregulation of DLX6-AS1 blocked the expression of Notch1, p21, and Hes1, leading to the suppression of proliferation, migration and invasion in OC cells." (PMID 32774164, 2020). "We found none of NOTCH1 mutations in these regional metastatic lymph nodes, further supporting that NOTCH1 mutations associated with early stage and non-lymph node metastasis." (PMID 26528858, 2016).
lymph node metastasis (continued). "Moreover, greater possibility of lymph node metastasis (LNM) and higher tumor stages were linked with high Notch1 expression in NSCLC (pooled OR = 3.20, 95%CI: 1.81-5.65, p = 0.798 and I2 = 0.0%; pooled OR = 1.62, 95%CI: 1.00-2.62, p = 0.251 and I2 = 25.5%)." (PMID 25996086, 2015). "NOTCH1 has been reported to be a marker of poor prognosis, and increased expression of the NOTCH intracellular domain (NICD) was associated with the presence of lymph node metastasis and worse survival." (PMID 25954607, 2015). "By statistical analyses, it was observed that negative Notch-1 expression was significantly associated with advanced clinical stage (P = 0.001) and lymph node metastasis (P = 0.026) in LAD patients." (PMID 24423157, 2013). "Furthermore, our study showed the prognostic relevance of NOTCH1, with higher expression being associated with increased survival and no lymph node metastasis." (PMID 25954607, 2015). "Specifically, the mutation frequencies of CDK6, MET, and NOTCH1 noticeably lower in cases with stage N0 than in those with stage N ≥ 1, whereas LRP1B mutation frequency was remarkably higher in cases without lymph node metastasis." (PMID 34152098, 2021). "CDK6, MET, NOTCH1, and LRP1B mutation frequencies showed significant differences in cases with (N ≥ 1) or without (N = 0) lymph node metastasis." (PMID 34152098, 2021). "While NOTCH1 expression negatively correlated with both clinical stages and lymph node metastasis, NICD1 expression did not significantly correlate with any of them." (PMID 26491213, 2015). "Furthermore, the NOTCH1 expression level in the tumors positively correlated with not only their TNM stages (the tumor/node/metastasis cancer staging system) and lymph node metastasis but also shorter patients' postoperative survival time." (PMID 26491213, 2015). "NF-κB expression in tumor cells was significantly correlated with lymph node metastasis (χ2 = 32.727, P = 0.001), LVD (χ2 = 4.312, P = 0.038), VEGF-C expression (χ2 = 4.241, P = 0.039), podoplanin expression (χ2 = 8.076, P = 0.004), and Notch1 expression (χ2 = 9.675, P = 0.002)." (PMID 21939555, 2011). "Taken together, we present a novel clinicopathological correlation such that expression of Notch pathway components and activated NOTCH1 levels predispose TSCC patients to lymph node metastasis, and that non-smokers TSCC patients tend to have higher NOTCH1 levels as compared to smokers." (PMID 27391340, 2016).
medulloblastoma (21 papers, 2007 to 2024). A malignant, invasive embryonal neoplasm arising from the cerebellum. "Herein, the NOTCH1 pathway was implicated as an important contributor to the invasion and migration abilities of group 3 medulloblastoma cells." (PMID 37568705, 2023). "Moreover, Group 3 medulloblastoma spinal metastases expressed higher levels of NOTCH1 pathway-associated genes compared with the primary tumors." (PMID 30297829, 2018). "To further assess the role of NOTCH1 in Group 3 medulloblastoma stem cell properties, we sorted the NOTCH1+ and NOTCH1− medulloblastoma cells from primary tumors of the cerebella and metastatic tumors of the spine of MB002 and D425 xenografted mice." (PMID 30297829, 2018). "Our findings suggest that NOTCH1-induced medulloblastoma metastasis occurs through TWIST1-induced BMI1 activation." (PMID 30297829, 2018). "NOTCH1+ medulloblastoma cells from both primary and metastatic tumors exhibited higher secondary neurosphere forming ability and increased clonogenicity than NOTCH1− cells, as determined by limiting dilution analysis." (PMID 30297829, 2018). "Mice injected with doxycycline-treated, and hence decreased NOTCH1 expressing, medulloblastoma cells (shNotch1 + Dox) presented lower frequency of spinal metastases compared with control cells (shNotch1−Dox)." (PMID 30297829, 2018). "We also show that NOTCH1+ medulloblastoma cells are responsible for the self-renewal of both the primary and metastatic tumor compartments of Group 3 medulloblastoma." (PMID 30297829, 2018). "For instance, Notch2 suppresses the effects of Notch1 in mesothelioma, but in medulloblastoma, Notch2 actually stimulates tumorigenesis, whereas Notch1 inhibits it." (PMID 29342862, 2018). "We have unified metastatic activity with self-renewal activity in Group 3 medulloblastoma under one common molecular pathway–NOTCH1." (PMID 30297829, 2018). "To further understand the effects of differential NOTCH1 expression in Group 3 medulloblastoma, we conducted a pathway enrichment analysis of the 154 significant genes (q < 0.1) and identified 135 significantly enriched pathways (q < 0.05)." (PMID 30297829, 2018). "NOTCH1 expression and activity are directly related to medulloblastoma metastasis and decreased survival rate of tumor-bearing mice." (PMID 30297829, 2018). "To test if NOTCH1 was necessary for Group 3 medulloblastoma metastasis, we inhibited its expression with shRNA against NOTCH1 and assessed the ability of medulloblastoma cells to generate spinal metastasis." (PMID 30297829, 2018). "In sum, these data corroborate the notion that Notch1 and Notch2 play different roles in medulloblastoma tumor growth." (PMID 29993038, 2018). "Here we show that NOTCH1 signaling pathway regulates both the initiation of metastasis and the self-renewal of medulloblastoma." (PMID 30297829, 2018). "We also compared NOTCH1 expression in Group 3 medulloblastoma patients, stratifying by presence (M+) or absence (M0) of metastasis at diagnosis (Cavalli Dataset11), and found that NOTCH1 expression is higher in M + patients." (PMID 30297829, 2018). "Here, the authors show that in Group 3 medulloblastoma NOTCH1 activates BMI1 through the activation of TWIST1, driving metastasis and self-renewal, and in mouse models a NOTCH1 blocking antibody decreased spinal metastases." (PMID 30297829, 2018). "As an in vitro surrogate of metastasis, we first compared the invasive properties between Group 3 medulloblastoma cells isolated from primary tumors (predominantly NOTCH1−) and spinal metastasis (predominantly NOTCH1+)." (PMID 30297829, 2018).
medulloblastoma (continued). "Our data suggest that Group 3 medulloblastoma cells that metastasize to the spinal cord arise from a distinct subpopulation of tumor cells with increased NOTCH1 pathway activity and expression." (PMID 30297829, 2018). "We then isolated whole medulloblastoma cells from primary mouse tumors in the cerebella (low frequency of NOTCH1+ cells) and from spinal metastases (high frequency of NOTCH1+cells) and re-transplanted into mouse cerebella." (PMID 30297829, 2018). "Human Group 3 medulloblastoma cerebellar xenografts were harvested and separated into NOTCH1+ and NOTCH1− cells by flow cytometry." (PMID 30297829, 2018). "In GBM and in medulloblastoma, the frequency and the intensity of Notch2 expression is higher than that of Notch1." (PMID 21078177, 2010). "In fact, in medulloblastoma, Notch2 is preferentially expressed in proliferating progenitors, while Notch1 in postmitotic differentiated cells." (PMID 21078177, 2010). "In the early exploration of medulloblastoma, it was recognized that hypoxia-induced hypoxia-inducible factor (HIF)-1α could sustain Neurogenic locus notch homolog protein 1 (Notch 1) in its active form by preserving medulloblastoma CSC viability and expansion." (PMID 37370764, 2023). "As a result, the intrathecal administration of anti-NOTCH1 Negative Regulatory Region antibody (anti-NRR1) in mice bearing group 3 medulloblastomas resulted in an attenuation of the metastatic potential of these tumors and a survival advantage for the treated mice." (PMID 37568705, 2023). "The NOTCH1 pathway represents a promising target for therapy of Group 3 medulloblastoma." (PMID 30297829, 2018). "Finally, we analyzed NOTCH1 expression in primary Group 3 medulloblastoma biopsy samples from five patients." (PMID 30297829, 2018). "To determine whether NOTCH1+ cells exhibited increased metastatic potential in vivo, we sorted the NOTCH1+ and NOTCH1− human medulloblastoma cells from primary cerebellar xenografts and separately transplanted them into mouse cerebella." (PMID 30297829, 2018). "To determine whether NOTCH1+ cells represent medulloblastoma self-renewing tumor stem cells, we performed in vivo serial transplant assays." (PMID 30297829, 2018). "Furthermore, mice injected with NOTCH1 silenced Group 3 medulloblastoma cells presented higher survival rates." (PMID 30297829, 2018). "Finally, to assess the tumorigenic potential of more limited cell number injection, human Group 3 medulloblastoma cerebellar xenografts were harvested, and 100 cells of either NOTCH1+ or NOTCH1- were injected into mouse cerebella." (PMID 30297829, 2018). "Furthermore, mice transplanted with NOTCH1+ medulloblastoma cells exhibited higher mortality rate than mice transplanted with NOTCH1− cells." (PMID 30297829, 2018). "NOTCH1-silenced medulloblastoma cells express lower levels of MYC." (PMID 30297829, 2018). "Whether NOTCH1+ primary and NOTCH1+ metastatic medulloblastoma cells represent the same population of cells or contain genomic differences is still unknown." (PMID 30297829, 2018). "Furthermore, inhibition of NOTCH1 pathway activity reduces medulloblastoma metastasis and increases survival." (PMID 30297829, 2018). "Finally, NOTCH1+ Group 3 medulloblastoma cells are more invasive in matrigel chambers than NOTCH1−cells." (PMID 30297829, 2018). "Due to the increased expression of surface NOTCH1 and NICD1 in Group 3 medulloblastoma spinal metastasis, we hypothesized that NOTCH1 expressing cells drive spinal metastasis in Group 3 medulloblastoma." (PMID 30297829, 2018). "Also, NOTCH1+ medulloblastoma cells from primary tumors express higher levels of CD15 and Ki67 than NOTCH1− medulloblastoma cells from the same tumors." (PMID 30297829, 2018). "Moreover, Notch2 was shown to promote tumorigenesis of medulloblastoma, whereas, Notch1 inhibited tumor growth." (PMID 25601901, 2014).